SIRT1 (sirtuin 1)
Diseases named in the same sentence as SIRT1 in open-access papers (continued):
Sharing a sentence is not in itself a finding about the gene and the disease.
cancer (continued). "SIRT1 overexpression has been reported in several human cancers, it was generally associated with poor prognosis and poor overall survival, whereas reduced SIRT1 expression was consistent with a tumor-suppressor role." (PMID 29340027, 2017). "Outside of its specific roles identified in CSCs, SIRT1 is also known to regulate the stemness‐associated Wnt signaling pathway in several non‐stem cancer cell contexts." (PMID 28994177, 2017). "In contrast, other studies indicate that SIRT1 levels are high in cancer samples and this is associated with poor prognosis and metastasis." (PMID 26905733, 2016). "The high expression of SIRT1 in fibroblasts is associated with poor prognosis in this cancer population." (PMID 26992208, 2016). "SIRT1 has been implicated in the cell cycle, as well as apoptosis and cancer metastasis, but its exact role in carcinogenesis remains controversial." (PMID 27793039, 2016). "Conversely, when cancer cells were cultured in the conditioned media from SIRT1-deficient fibroblasts, the number of cancer colonies was significantly diminished." (PMID 26992208, 2016). "In terms of cellular signaling, studies in the fields of cancer and inflammation suggest that NF-kB and SirT1 activities are causatively or accidentally associated with two alternative modes of cellular functioning." (PMID 26041885, 2015). "Correlation between DNA damage-associated NAD+ depletion and decrease of SIRT1 activity in older rats suggested that NAD+ is important for cancer prevention and longevity." (PMID 26544624, 2015). "Current researches focus on the biological functions of SIRT1 in obesity associated metabolic diseases, cancer, aging, cellular senescence, inflammatory signaling in response to environmental stress, development and placental cell survival." (PMID 26318035, 2015). "In cancer pathogenesis; SIRT1 plays a bivalent role; functional loss of SIRT1 promotes tumorogenesis because of genomic instability." (PMID 25895126, 2015). "There was a significant decrease in telomerase activity in SIRT1 knockdown sample, suggesting an existing cross-talk between these two key cancer-associated proteins." (PMID 26459286, 2015). "Interaction of FOXO1 (a direct activator of ATGL) and SIRT1 (an activator of FOXO1) led to activation of FOXO1 which is linked with increased tumorigenicity of cancer cells via acylglycerol kinase." (PMID 25569080, 2015). "In mammals, SIRT1 expression, has been shown to be induced by CR and delay age and associated diseases, such as cancer, atherosclerosis and diabetes." (PMID 25895126, 2015). "Double-stranded breaks can cause the development of cancer and also result in the induction of a hypermethylated state with the aid of silencing factor, SIRT1." (PMID 26459286, 2015). "High expression of SIRT1 was associated with a poor cancer-specific survival prognosis by both univariate (P = 0.007) and multivariate (P = 0.05) analyses." (PMID 25146318, 2014). "SIRT1 has also been reported to improve healthy ageing and to protect against metabolic syndrome-associated cancer." (PMID 25541949, 2014). "This is not surprising as dysregulated cellular metabolism is a hallmark of cancer cells, and SIRT1 has been shown to affect metabolic processes." (PMID 24743044, 2014). "Further, the overexpression of SIRT1 has been linked to poor disease prognosis and survival in variety of cancers." (PMID 24743044, 2014).
cancer (continued). "To address this question, we systematically analyzed the impact of loss of SIRT1 function on several members of the Frizzled (FZD) family of receptors in two cancer cell lines previously shown to be sensitive to SIRT1 inhibition, MDA-MB-231 and T-47D cells." (PMID 24897117, 2014). "The protein deacetylase SIRT1 has been implicated in the regulation of a large number of cellular processes that are thought to be required for cancer initiation and progression." (PMID 24278473, 2013). "Our previous studies of cancer development employed animals carrying a null mutation for Sirt1 and used 2-stage skin carcinogenesis and APC-dependent colon cancer." (PMID 24278473, 2013). "Salermide is an inhibitor of Sirt1 and Sirt2 that causes apoptotic tumor-specific cell death in a variety of human cancer cell lines." (PMID 24069483, 2013). "SIRT1 has been implicated in signaling pathways underlying various diseases, including: diabetes, cardiovascular disease, neurodegeneration, cancer, aging, and obesity." (PMID 24360018, 2013). "There is also an abundant literature indicating that the functional dysregulation of SIRT1 is associated with many age-related diseases, e.g., metabolic syndrome, cardiovascular and neurodegenerative diseases, and cancer." (PMID 23434668, 2013). "The expression of SIRT1 increases resistance to anticancer agents and is associated with progression of cancers and poor prognosis of cancer patients." (PMID 24019980, 2013). "SIRT1 was found to be important for maintaining genome stability, loss of which is a hallmark of cancer, and to mediate DNA damage repair." (PMID 23799088, 2013). "SirT1, the best studied to date, has been implicated in processes as varied as metabolism, differentiation, cancer, stress response and cell senescence." (PMID 21307403, 2011). "Ubiquitous expression of the SIRT1-ΔExon8 splice variant was evident in a panel of 12 normal mouse tissues, and in mouse cell lines of normal- or cancer-origin." (PMID 20975832, 2010). "For example, loss ofmiR-34a leads to SIRT1 overexpression in cancer.Some results point to direct binding ofmiR-34a to the SIRT1 3'-UTR whereas others have suggested indirect regulationof SIRT1 by miR-34a." (PMID 20634564, 2010). "Several studies have linked SIRT1 to cancer stemness and resistance to conventional therapy." (PMID 40664665, 2025). "Cellular Context: Changes in cellular pathways (such as insulin resistance, inflammation, or mutations associated with cancer) may alter how SIRT1 interacts with its targets or prevent its deacetylase activity." (PMID 41300302, 2025). "In this study, we conducted a comprehensive analysis via multiple databases, including TCGA, GTEx, TISIDB, cBioPortal, STRING, GSCALite, and CancerSEA, to explore the gene expression, prognosis, protein interactions, and associated signaling pathways of SIRT1 in pan-cancer." (PMID 39845948, 2024). "Summarizing the underlying mechanisms involved in SIRT1-mediated cancer regulation." (PMID 39403142, 2024). "Moreover, SIRT1 expression is strongly associated with immunoregulatory factors across different cancers." (PMID 39845948, 2024). "Using the cBioPortal online website, gene mutations of SIRT1 in pan-cancer were analyzed." (PMID 39845948, 2024). "Despite the widespread occurrence of SIRT1 mutations across various cancers, the mechanisms underlying its role in cancer initiation and progression may differ." (PMID 39845948, 2024).
cancer (continued). "Maintaining adequate intracellular NAD+ levels and proper SIRT1 nuclear activity may therefore be critical for preventing DNA damage, genomic instability, and chronic inflammation, which contribute to increased cancer risk." (PMID 39766219, 2024). "R-loops were highly prevalent in cancer cells harboring mutated SIRT1 or the depletion of SIRT1." (PMID 37998365, 2023). "Previous studies reported that SIRT1 could improve healthy ageing and protect against metabolic-syndrome-associated cancers." (PMID 36552538, 2022). "NAD+-dependent deacetylase SIRT1 regulates many different biological processes, thus being involved in pathogenic conditions such as metabolic diseases, neurogenerative disorders and cancer." (PMID 35337137, 2022). "Taken together, these findings suggested that FOXK2 and FOXO3 may be affected by opposing SIRT1‐associated molecular mechanisms under stress conditions, although the effects on cancer cell apoptosis were similar." (PMID 34866322, 2022). "Sirt1 expression plays critical roles in mammalian health and disease development and is often associated with the most complex physiological processes, including metabolism, the onset of cancer, and aging." (PMID 33889076, 2021). "The present study selected sirtuin 1 (SIRT1), associated with different types of cancers." (PMID 34942940, 2021). "Melatonin was first implicated in modulating nuclear SIRT1 during the biological process of cancer." (PMID 32566095, 2020). "However, research has been performed on the association of SIRT1 polymorphisms and risk of other cancers." (PMID 32098999, 2020). "Context-dependent alterations of chromatin by SIRT1 may underlie the observation that manipulation of SIRT1 levels can exert both protective and stimulatory effects on cancer development." (PMID 29578371, 2018). "It has been reported that SIRT1 is associated with metastasis in various cancers." (PMID 29374154, 2018). "High level of SIRT-1 usually implicated poor prognosis in patients with cancer." (PMID 29552311, 2018). "However, decreases in SIRT1 have been associated with cancer protection, which also is involved in healthful aging." (PMID 29654651, 2018). "Second SIRT1 expression has been associated with other molecular biomarkers for cancer prognosis." (PMID 28977971, 2017). "The shift of cancer metabolism from glycolysis to mitochondrial oxidative phosphorylation is associated with the development of resistance to chemotherapy, and this process seems to be promoted by the enhancement of SIRT1/PCG1α-driven ROS scavenging defences." (PMID 28904402, 2017). "To search for fibroblast-derived factors responsible for cancer proliferation, we applied conditioned media from control, SIRT1-overexpressing, and SIRT1-deficient MEF-1 cells to protein profiling arrays, and compared the intensities of spots among three groups." (PMID 26992208, 2016). "Accordingly, the inhibition of some of these signaling pathways may be associated with the inhibitory action of SIRT1 on cancer growth." (PMID 26992208, 2016). "For example, there are several proteins (e.g., WNT5A, RACK1, SIRT1 and several F-box proteins) whose expression levels appear to correlate with the risk to acquire certain cancers, yet the same proteins have been observed to confer protection against cancers in other paradigms." (PMID 25453033, 2014).
cancer (continued). "Therefore, we suggest that Sirt1 participates in the initiation of tumors and furthermore its expression is more closely associated with medium-term and advanced stages of cancer and tumor development." (PMID 24959282, 2014). "SIRT1 is also over-expressed and required for cell survival in pancreatic cancers, has been implicated in the non-solid tumour chronic myelogenous leukaemia and suggested as an anti-cancer target for medulloblastoma." (PMID 24258275, 2013). "This phenomenon raised the question of whether the increased expression of SIRT1 in cancer is the cause of the cancer or the consequence of the deregulation of key factors involved in the development of cancer." (PMID 24019980, 2013). "For example, miR-34a represses the production of Bcl-2 and SirT1, two proteins displaying high levels of expression in cancer cells and implicated in promoting proliferation and cell survival, although miR-34a does not affect Bcl-2 expression levels in all cell systems." (PMID 23325049, 2013). "Thus, upregulation of SIRT1 in tumors was found to be associated with unsatisfactory therapeutic outcomes in some cancer patients." (PMID 23050959, 2012). "Besides inhibiting abnormally activated proinflammatory signaling and subsequently preventing inflammation-associated cancer, SIRT1 participates in suppression of multistage carcinogenesis via other mechanisms." (PMID 23050959, 2012). "In spite of the increasing knowledge about the protective role of Sirt1 on age-associated pathologies that include neurodegenerative and cardiovascular disease, metabolic disorders and cancer [reviewed in 5], the role of Sirt1 in muscle aging is poorly understood." (PMID 21483036, 2011). "Thus, through improving metabolic conditions by increasing Sirt1 activity, it is possible to both extend lifespan and reduce cancer risk in humans in the foreseeable future." (PMID 21549004, 2011). "The SIRT1-ΔExon8 splice variant was ubiquitously expressed in all 12 normal human tissues tested, and in a panel of 16 human epithelial cell lines of normal- or cancer-origin; although SIRT1-FL was more abundant in each case." (PMID 20975832, 2010). "Furthermore, with contribution of the stress-related protein SIRT1, the break can lead to the onset of aberrant CpG island DNA methylation, which is frequently associated with tight gene silencing in cancer." (PMID 18704159, 2008). "Among these low-penetrance genes that may play a significant role in cancer risk is SIRT1." (PMID 40507674, 2025). "Furthermore, the loss of long non-coding RNA DACT3-AS1 in exosomes derived from cancer-associated fibroblasts (CAFs) promotes gastric tumor malignant transformation and oxaliplatin resistance by affecting the miR-181a-5p/SIRT1 axis, a process involved in the regulation of ferroptosis." (PMID 40109363, 2025). "Additionally, the high heterogeneity of cancer may influence the effectiveness and specificity of SIRT1 as a diagnostic or prognostic biomarker, and the therapeutic efficacy of SIRT1-based interventions may vary among individual patients." (PMID 39845948, 2024). "In addition, AMPK could induce apoptosis by activating the AMPK–sirtuin 1 pathway or triggering reactive oxygen species‐associated apoptosis in various cancers." (PMID 38222315, 2024). "Additionally, SIRT1 inhibitors may interfere with the autophagic survival pathways, further increasing cancer cell susceptibility to stress and cytotoxicity." (PMID 39403142, 2024). "The SIRT1/autophagy interplay may serve as a prognostic indicator of tumor recovery risk in cancer patients and could help in the development of a novel therapeutic approach to cancer treatment." (PMID 38397988, 2024).
cancer (continued). "However, cancer cells activated dormant replication origins, genome-wide, during long-term proliferation with mutated or depleted SIRT1, whereas, in primary cells, the aging-associated SIRT1-mediated activation of dormant origins was restricted to rDNA loci." (PMID 37998365, 2023). "As the most well-studied sirtuin, SIRT1 has been implicated in many physiological and pathophysiological processes, including the circadian clock, neuronal protection, caloric restriction, cell cycle arrest, apoptosis, glucose and lipid metabolism, cellular senescence, and cancer." (PMID 31209362, 2020). "However, SIRT1 is also associated with cancer cell growth, apoptosis, and tumorigenesis." (PMID 31747893, 2019). "However, in vivo experiments indicate that other mutations in relevant cancer-related pathways might determine the function of SIRT1, thus, the role of SIRT1 should be viewed as context dependent." (PMID 31608282, 2019). "Future studies should clarify for chronic treatment of patients at risk of cancer, whether a less tight SIRT1 inhibition is indeed sufficient for cancer prevention with fewer side effects, compared to high-affinity SIRT1 inhibitors under development as anti-cancer drugs." (PMID 30739913, 2019). "Therefore, hnRNP A1 and SIRT1 may represent potential diagnostic and therapeutic targets for certain cancer treatments." (PMID 27613566, 2016). "This enhancement of SIRT1 in aging cells may increase cell survival as well as cancer risk." (PMID 25486244, 2014). "Although SIRT1 activation is often protective in metabolic and cardiovascular and neurovascular settings, its role in cancer remains dualistic, acting as both tumor suppressor and promoter." (PMID 42256526, 2026). "In particular, SIRT1 shows dual roles, functioning both as a tumor suppressor or an oncogene, contributing to cancer initiation, progression, and metastasis as well as chemotherapy resistance." (PMID 41898317, 2026). "Conversely, activation of SIRT1 can prevent the development of high‐grade prostatic intraepithelial neoplasia lesions in a Pten−/− mouse model at the pre‐cancer stage, hinting at its potential tumor‐suppressive functions." (PMID 40855785, 2026). "SIRT1 has garnered significant attention in cancer research due to its dual roles in oncogenesis and tumor suppression." (PMID 40855785, 2026). "The NAD + dependent deacetylase sirtuin-1 (SIRT1) is known to elicit cellular defenses against aging, cancer, and other aberrant pathologies." (PMID 42039642, 2026). "In our recent study, we investigated the high and low expression of SIRT1, a NAD+‐dependent histone deacetylase, also known as HDAC class III enzyme, in GC, CC, and RC cancers and its association with tumor biological characteristics." (PMID 41020376, 2025). "The therapeutic potential of SIRT1 in modulating ferroptosis is vast and spans a range of diseases, including neurodegenerative disorders, cancer, and kidney diseases." (PMID 40109363, 2025). "This homeostatic maintenance, induced by the regulation of the FOXO-3 protein, highlights the importance of SIRT1 for aging and cancer." (PMID 39858038, 2025). "BM-MSCs-exo have been proposed in apoptotic regulation resulting from a decrease in BCL and SIRT1 protein leading to the suppression of cancer cell growth and apoptosis induction." (PMID 40732337, 2025). "These inhibitors serve as potential therapeutic agents by targeting SIRT1’s role in tumor survival and proliferation, offering a strategy to sensitize cancer cells to treatment." (PMID 40052151, 2025).